PYROXD2 (pyridine nucleotide-disulphide oxidoreductase domain 2)
Description:
Probable oxidoreductase that may play a role as regulator of mitochondrial function.
Synonyms: C10orf33; FLJ23849; FP3420; YUEF
Tractability: PROTAC: its protein half-life has been measured.
Gene: Protein-coding gene on chromosome 10 (98,383,565 to 98,415,210, reverse strand). Ensembl gene ENSG00000119943.
Subcellular location: Mitochondrion matrix
Subcellular location (Human Protein Atlas): Mitochondria
Gene Ontology:
Molecular function: protein binding; oxidoreductase activity
Biological process: mitochondrion organization
Cellular component: mitochondrial matrix; mitochondrion
Genetic constraint (gnomAD): Loss-of-function variants: 62 observed, 66.88 expected, observed/expected ratio (o/e) 0.93, 90% interval 0.75 to 1.14. The upper end of that interval is the gene's LOEUF score, 1.14, which puts it in group 5 of 6, group 1 being the genes least tolerant of losing a copy. Missense variants: 722 observed, 737.98 expected, observed/expected ratio (o/e) 0.98, 90% interval 0.92 to 1.04. Synonymous variants: 276 observed, 300.83 expected, observed/expected ratio (o/e) 0.92, 90% interval 0.83 to 1.01.
Homologues: Orthologues: chimpanzee PYROXD2 (99% identical), macaque PYROXD2 (96% identical), pig PYROXD2 (87% identical), guinea pig PYROXD2 (86% identical), rat Pyroxd2 (86% identical), dog PYROXD2 (86% identical), mouse Pyroxd2 (85% identical), tropical clawed frog pyroxd2 (66% identical), rabbit PYROXD2 (57% identical), Caenorhabditis elegans F37C4.6 (51% identical). Paralogues in human: RETSAT (20% identical), BLOC1S2 (3% identical).
Diseases named in the same sentence as PYROXD2 in open-access papers:
PYROXD2 is named in the same sentence as 16 diseases in open-access papers, as found by Europe PMC text mining. Sharing a sentence is not in itself a finding about the gene and the disease. The quoted sentences say what the papers report.
adenoma (1 paper, 2025). A neoplasm arising from the epithelium. "Among them, 3 genes (NUDT13, PYROXD2, and YPEL3) were validated through RT‐qPCR using a cohort comprising 36 paired early‐stage CRC samples and 14 paired adenomas, as well as through datasets from UCSC Xena." (PMID 39921866, 2025).
basal cell carcinoma (1 paper, 2022). A carcinoma involving the basal cells. "PYROXD2 is differentially expressed in basal cell carcinoma and is localized in the mitochondrial inner membrane, where it is associated with increased cell proliferation and ATP production, highlighting its role in melanoma survival and metabolism." (PMID 35606887, 2022).
gastric carcinoma (1 paper, 2019). A carcinoma that arises from epithelial cells of the stomach. "Interestingly, the tongue SCC ITOC-02 cell line had truncating mutations in a few genes which are rarely associated with some cancers, PYROXD2, PCMTD1 reported to be mutated in hepatocellular cancer and PABCP1 reported to be upregulated in gastric carcinoma and targeting miR-34c38." (PMID 31164688, 2019).
limb-girdle muscular dystrophy (1 paper, 2020). Limb-girdle muscular dystrophy (LGMD) is a heterogeneous group of muscular dystrophies characterized by proximal weakness affecting the pelvic and shoulder girdles. "The physiological role of PYROXD2, particularly in skeletal muscle, remains largely unclear but recent data show that genetic variants in its family member PYROXD1 induces early‐onset myopathy and limb girdle muscular dystrophy characterized by abnormal myofibrils, nuclei, and mitochondria." (PMID 32892688, 2020).
melanoma (1 paper, 2022). A malignant, usually aggressive tumor composed of atypical, neoplastic melanocytes. "We have found a concordant relationship between lower promoter methylation and higher gene expression levels for Pyroxd2 and Ptgfrn from the malignancy signature, which was also associated with the poorest survival in melanoma patients." (PMID 35606887, 2022). "We found a concordant relationship between DNA methylation and transcriptional levels for genes from the malignancy (Pyroxd2 and Ptgfrn) and metastasis (Arnt2, Igfbp4 and Ptprf) signatures, which were both also correlated with melanoma prognosis." (PMID 35606887, 2022).
sarcoma (1 paper, 2013). A usually aggressive malignant neoplasm of the soft tissue or bone. "Using the DNA methylation status of a CpG site in the promoter of PYROXD2, a putative pyridine nucleotide-disulfide oxidoreductase gene with an uncharacterized functional role, we were able to separate the entire cluster 7 from the whole sarcoma collection with an AUC of 100%." (PMID 24345474, 2013). "The DNA methylation status of a CpG site within the promoter of PYROXD2 was the most reliable differentiation marker for sarcoma cluster 7 (mainly SS samples) and could be used as a unique marker for the pairwise comparison of sarcoma cluster 7 with all other sarcoma clusters." (PMID 24345474, 2013). "Therefore, the differential DNA methylation status of just one CpG site in the promoter of PYROXD2 may help differentiation between SS and MPNST or the other sarcoma subtypes analyzed in this study." (PMID 24345474, 2013).
cancer (2 papers, 2019 to 2020). A tumor composed of atypical neoplastic, often pleomorphic cells that invade other tissues.
mitochondrial disease (1 paper, 2022). "In the present paper, we report biallelic variants in PYROXD2 identified by genome sequencing in a patient with suspected mitochondrial disease." (PMID 35055180, 2022).
PYROXD2 also shares sentences with these, for which no sentence is quoted: tumor (2 papers); hepatoma (1); infection (1); myopathy (1); Obesity (1); prostate carcinoma (1); renal cell carcinoma (1); type 2 diabetes (1).